COG1 (component of oligomeric golgi complex 1)
Description:
Required for normal Golgi function.
Synonyms: KIAA1381; LDLB; CDG2G
Tractability: Antibody: UniProt places it where antibodies can reach, with high confidence. PROTAC: ubiquitination databases record sites on it; its protein half-life has been measured.
Target class: Other cytosolic protein
Gene: Protein-coding gene on chromosome 17 (73,193,038 to 73,209,422, forward strand). Ensembl gene ENSG00000166685.
Subcellular location: Golgi apparatus membrane
Pathways (Reactome):
Vesicle-mediated transport: COPI-mediated anterograde transport; Intra-Golgi traffic; Retrograde transport at the Trans-Golgi-Network
Disease: Dengue Virus-Host Interactions
Gene Ontology:
Molecular function: protein binding
Biological process: Golgi organization; retrograde transport, vesicle recycling within Golgi; intra-Golgi vesicle-mediated transport
Cellular component: Golgi apparatus; Golgi transport complex; endoplasmic reticulum-Golgi intermediate compartment membrane; Golgi membrane; trans-Golgi network membrane
Genetic constraint (gnomAD): Loss-of-function variants: 62 observed, 106.69 expected, observed/expected ratio (o/e) 0.58, 90% interval 0.47 to 0.72. The upper end of that interval is the gene's LOEUF score, 0.72, which puts it in group 2 of 6, group 1 being the genes least tolerant of losing a copy. Missense variants: 1,164 observed, 1,274.6 expected, observed/expected ratio (o/e) 0.91, 90% interval 0.87 to 0.96. Synonymous variants: 454 observed, 514.33 expected, observed/expected ratio (o/e) 0.88, 90% interval 0.82 to 0.95.
Gene-disease validity (ClinGen):
ClinGen rates the evidence that COG1 causes each of these diseases.
COG1-congenital disorder of glycosylation (autosomal recessive): Moderate. COG1-CDG is an extremely rare form of CDG syndrome characterized clinically in the few cases reported to date by variable signs including microcephaly, growth retardation, psychomotor retardation and facial dysmorphism.
Homologues: Orthologues: chimpanzee COG1 (99% identical), macaque COG1 (98% identical), pig COG1 (88% identical), dog COG1 (87% identical), rat Cog1 (86% identical), mouse Cog1 (86% identical), rabbit COG1 (64% identical), tropical clawed frog cog1 (64% identical), zebrafish cog1 (56% identical), Drosophila melanogaster Cog1 (24% identical), Caenorhabditis elegans cogc-1 (18% identical).
Diseases named in the same sentence as COG1 in open-access papers:
COG1 is named in the same sentence as 13 diseases in open-access papers, as found by Europe PMC text mining. Sharing a sentence is not in itself a finding about the gene and the disease. The quoted sentences say what the papers report.
developmental delays (1 paper, 2025). "Mutations of COG1 leads to COG1-CDG, causing facial dysmorphism, developmental delays, intellectual disability, seizures and other health problems, reflecting abnormal hepatic, gastrointestinal, skeletal and cardiac functioning." (PMID 41583011, 2025).
dwarfism (1 paper, 2023). "To date, fewer than ten COG1-CDG patients have been described, presenting with dwarfism, facial dysmorphism, microcephaly and psychomotor delay." (PMID 37239976, 2023).
gastric lymphoma (1 paper, 2016). An extranodal lymphoma that arises from the stomach with the bulk of the mass located in the stomach. "28S rRNA has been identified as a novel fusion partner of carcinoma-related genes such as BCL6, BCL11B, IGKV3-20, and COG1 in gastric lymphoma or hematopoietic tumors." (PMID 27517048, 2016).
cancer (2 papers, 2016 to 2022). A tumor composed of atypical neoplastic, often pleomorphic cells that invade other tissues. "For instance, the Greedy Decision Forest selected a module comprising of three genes for the cancer type experiment, namely COG1, COG3, and COG5." (PMID 36207536, 2022).
skeletal dysplasia (1 paper, 2021). Any Mendelian diseases that affects growth and development of the skeleton. "While patients with COG8-CDG displayed severe skeletal dysplasia, COG1-CDG and COG8-CDG patients had a significantly milder clinical presentation." (PMID 34441372, 2021). "Skeletal dysplasia was also reported as the main clinical feature of patients with COG7-CDG, COG1-CDG and COG8-CDG." (PMID 34441372, 2021).
COG1 also shares sentences with these, for which no sentence is quoted: Cerebellar atrophy (1 paper); Failure to thrive (1); Immunodeficiency (1); Intellectual disability (1); keratosis pilaris (1); microcephaly (1); neurodevelopmental disorder (1); primordial dwarfism (1).